IL10 (interleukin 10)
Diseases named in the same sentence as IL10 in open-access papers (continued):
Sharing a sentence is not in itself a finding about the gene and the disease.
pulmonary fibrosis (continued). "It was reported that IL10, ARG1, and AKT1 were all associated with the macrophage activation and apoptosis in pulmonary fibrosis." (PMID 31105564, 2019). "All groups, A. suum infection, bleomycin-induced lung fibrosis, and comorbidity of both pathologies, revealed equal levels of IL-10; in all groups analyzed it was reduced when compared to control mice." (PMID 31765381, 2019). "Interleukin 10 can also be considered as an anti-inflammatory drug in preventing pulmonary fibrosis in patients with idiopathic pulmonary fibrosis (IPF)." (PMID 31363402, 2019). "Cytokines like IFN-γ and IL-10 are generally related to counterbalance the progression of pulmonary fibrosis." (PMID 31765381, 2019). "Overexpression of IL-10, a type 2 cytokine and a potent inhibitor of type 1 inflammation, in mouse lungs augments lung fibrosis and Th2 responses induced by silica particles through suppressing type 1 inflammatory responses." (PMID 29872441, 2018). "IL-10 deficiency accelerates kidney inflammation and fibrosis in the unilateral ureteral obstruction mouse model, and treatment with IL-10 ameliorates lung fibrosis." (PMID 29466999, 2018). "Insufficient B10 clearly inhibited Treg and decreased the level of IL-10, which amplified inflammation and attenuated lung fibrosis by promoting the Th1 immune response." (PMID 29872441, 2018). "Our data showed that antofine can modulate the expression of lung fibrosis‐related cytokines such as IL‐10 and IL‐33." (PMID 28805975, 2017). "Our selection includes cytokines previously associated with the lung response to radiation in both mice and humans such as Il6 and Tnfα) as well as pulmonary fibrosis-promoting Il1β, Il13 and Il17) and anti-fibrotic mediators Il10 and Ifnγ." (PMID 25889053, 2015). "While gene delivery of IL-10 has been showed to attenuate pulmonary fibrosis other investigators have found it only inhibited inflammation, but not fibrosis." (PMID 24742272, 2014). "Marked induction of lung fibrosis was observed in mice following long-term over-expression of IL-10 by fibrocyte recruitment and M2 macrophage activation." (PMID 24023968, 2013). "Transcription factor STAT3 is associated with chronic inflammatory diseases and the transcription products of STAT3, such as IL-6, IL-10, and IL-17, are involved in the pathogenesis of pulmonary fibrosis." (PMID 23869224, 2013). "Martinez and colleagues noted that alveolar macrophages recovered from bronchoalveolar lavage (BAL) in patients with pulmonary fibrosis showed increased IL-10 mRNA expression." (PMID 23815594, 2013). "Collectively, these results demonstrate that MMP-8 is an important regulator of IL-10 in vivo and point this metalloprotease as a potential therapeutic target in lung fibrosis." (PMID 20949050, 2010). "IL-10 also correlates with increased disease severity, increased skin thickness, and the presence of pulmonary fibrosis." (PMID 16879746, 2006). "As already observed, a persisting increase of IL-10 production was observed in the FA model (silica) which paralleled the establishment of lung fibrosis." (PMID 16212659, 2005). "Altogether, we concluded that expression of IL-10 was intimately correlated with the amplitude of silica-induced lung fibrosis." (PMID 16212659, 2005). "Collectively, these observations strongly indicate that IL-10, an anti-inflammatory/Th2 cytokine, exacerbates the severity and pathology of lung fibrosis, at least in the mouse." (PMID 16212659, 2005). "Collectively, these findings showed that SP-D and IL-10 exhibited potential predictive abilities for the development of severe disease and pulmonary fibrosis, which also indicated that inflammatory and anti-inflammatory imbalance was linked to a poor outcome in SARS-CoV-2 infection." (PMID 40160824, 2025).
pulmonary fibrosis (continued). "At the molecular level, the zinc finger protein ZC3H4 has emerged as an important monocyte regulator capable of attenuating pulmonary fibrosis progression through interleukin-10 (IL-10)-mediated anti-inflammatory mechanisms, highlighting potential molecular targets for therapeutic intervention." (PMID 40650314, 2025). "AI-driven models could also predict patient-specific inflammatory dynamics, guiding the selection of IL-10 formulations or combination therapies for conditions like COPD or pulmonary fibrosis." (PMID 41312367, 2025). "However, treatment with saroglitazar or BrMSCs initiated 14 days after pulmonary fibrosis induction significantly (p < 0.05) reduced the IL-1β concentration and increased IL-10 levels compared to their levels in BLM-G." (PMID 38376539, 2024). "While IL-10 is often considered a canonical anti-inflammatory cytokine, it has been found that over-exposure to IL-10 induced fibrocyte recruitment and exacerbated lung fibrosis;43 thus, its excess production in VML may exacerbate dysregulated ECM deposition." (PMID 37468760, 2023). "Studies have shown that IL-10 has a therapeutic effect in pulmonary fibrosis." (PMID 36564791, 2022). "In mice, silica-induced pulmonary fibrosis is associated with low-intensity and transitory inflammation, characterized by increased production of anti-inflammatory cytokine IL-10, accounting for the ineffectiveness of anti-inflammatory therapy in mice with silica-induced pulmonary fibrosis." (PMID 36499287, 2022). "Lyve1hi MHCIIlo IMs secrete more IL-10 during steady-state, and in the absence of these IMs, the symptoms of pulmonary fibrosis were more severely manifested as measured by weight loss, collagen deposition, and immune cell infiltration." (PMID 36211428, 2022). "Such discoveries indicate that IMs participate in lung fibrosis through IL-10." (PMID 36211428, 2022). "Since it has been demonstrated that DCSL1 alleviates fibrosis and increases IL-10 levels in the bleomycin-induced lung fibrosis model in young mice, we tested the hypothesis that it could have the same efficacy in the aging heart." (PMID 32851570, 2021). "Moreover, M2 macrophages are an important regulator of pulmonary fibrosis, partially through the secretion of profibrotic interleukin-10 (IL-10) and TGF-β." (PMID 34859008, 2021). "However, intranasal administration of TGFβ1-expressing plasmid results in increased TGFβ1- and IL-10-producing Treg cells and ameliorates bleomycin-induced lung fibrosis in mice." (PMID 32676074, 2020). "Moreover, mice with IL-10-induced pulmonary fibrosis showed significantly increased numbers of M2 macrophages in both bronchoalveolar lavage and lung tissue than normal mice, which was associated with enhanced expression of C-C motif chemokine ligand 2 (CCL2)." (PMID 32708044, 2020). "IL-10 could induce lung fibrosis via promoting fibrocyte recruitment and M2 macrophage activation in a CCL2/CCR2 axis." (PMID 31105564, 2019). "Interestingly, IL-10 and IL-17 levels in bronchoalveolar lavage after pulmonary irradiation were shown to be inversely correlated to the severity of pulmonary fibrosis." (PMID 30998706, 2019). "Thus, the exact contribution of IL-10 to the development of pulmonary fibrosis in vivo remains undetermined." (PMID 29690905, 2018). "Genetic ablation of IL-10 abrogated the ameliorating effect of Tregs on pulmonary fibrosis." (PMID 29690905, 2018). "The results suggested that IL-10 from Tregs might have an impact on the resolution of BLM-induced pulmonary fibrosis, which supports the data from previous studies." (PMID 29690905, 2018). "We found a downregulated expression of IL-10 at day 28 after transplantation, which might indicate the benefit of low expression of IL-10 in lung tissue during pulmonary fibrosis prohibition exerted by AD-MSC transplantation." (PMID 29673394, 2018).
pulmonary fibrosis (continued). "In a mouse model of silica-induced lung fibrosis, interleukin-10-producing regulatory B cells could control lung inflammation and exacerbate lung fibrosis by inhibiting the T-helper 1 response and modulating the T-helper balance." (PMID 29208971, 2017). "As Th1 cytokine has been demonstrated to play important role in the progression of lung fibrosis, we can speculate that the downregulation of IL-10 accompanied with increased production of Th1 cytokine may strongly promote the fibrotic change in the lung." (PMID 28821283, 2017). "In addition to their immune suppressive properties, MSCs secrete a variety of anti‐fibrogenic proteins and enzymes such as interleukin‐10 (IL‐10), hepatocyte growth factor and matrix metalloproteinases and are effective in bleomycin‐induced lung fibrosis." (PMID 28186707, 2017). "Moreover, genetic delivery of IL-10 significantly attenuates the TGF-β production in the lung of mice with bleomycin-induced pulmonary fibrosis." (PMID 26199463, 2015). "Although persistent IL-10 production may lead to lung fibrosis, it is unknown whether the cytokine could accelerate fibrous tissue deposition in the endomyocardium of EMF patients." (PMID 25303100, 2014). "Recently, IL-10, a regulatory T cell (Treg) cytokine, has been found to trigger pulmonary fibrosis." (PMID 23869224, 2013). "Considering our earlier work that the inhibitory cytokine IL-10 increased significantly in silica-treated group, we had a reason to believe that Tregs did not manipulate Th17 response in an IL-10 dependent way in silica-induced lung fibrosis." (PMID 22615967, 2012). "Similarly, Arpin and coworkers found that high levels of IL-10 were protective against radiation induced symptomatic pulmonary fibrosis after thoracic radiotherapy, while elevation of IL-6 was associated with more severe lesions." (PMID 22216271, 2011). "To investigate the regulatory role of Treg cells in silica-induced lung fibrosis of mice mould, we next explored whether Treg cells regulated the immune homeostasis through IL-10 and/or TGF-β during the short- and long-term lung responses to silica particles." (PMID 21072213, 2010). "Since there is evidence that pulmonary fibrosis is a Th2-mediated process, we speculate that elevated lung levels of IL-10 may also contribute to the progression of fibrosis via its capacity to stimulate Th2 polarized responses." (PMID 16212659, 2005). "Lung IL-10 levels were related to the amplitude of pulmonary fibrosis." (PMID 16212659, 2005). "However, recent evidence in murine models of lung fibrosis suggests that IL-10 may be profibrotic, exacerbating Th2 responses, producing IL-4 and IL-13, the recruitment of fibrocytes, and M2 macrophage polarization." (PMID 36831337, 2023). "Interestingly, we observed an inconsistency in the expression of TGF-β and IL-10 in the lungs of BLM-induced pulmonary fibrosis mice, wherein TGF-β was significantly upregulated and was accompanied by a notable decrease in IL-10 expression, corroborating findings in the literature." (PMID 38259493, 2023). "For the treatment of respiratory diseases, the intratracheal administration of hydrogel combined with fibroblast growth factor and interleukin-10 (IL-10) could alleviate monocutarine-induced pulmonary hypertension and bleomycin-induced pulmonary fibrosis, respectively." (PMID 35619760, 2022). "Thus, IPF with higher levels of anti-MX1 IgA autoantibody might show more local production of TGF-β and IL-10, more apoptotic AECs in the lung, and progression of pulmonary fibrosis that is more rapid than would be found with lower levels of this autoantibody." (PMID 35391716, 2022). "Using IL-10 deficient animals, Kradin and coworkers have not found a difference in lung fibrosis." (PMID 20949050, 2010). "However, there are also reports of a profibrotic role of IL-10 in lung fibrosis induced by silica." (PMID 20949050, 2010).
pulmonary fibrosis (continued). "In mice treated with BLM, atRA attenuated the upregulation of IL-17A, IL-10, IL-6, EphA2, EphriA1, PI3K 110γ, Akt, IL-6, TNF-α, and TGFβ1, which reduced pulmonary fibrosis and significantly alleviated lung fibrosis." (PMID 40508111, 2025). "Together, these findings demonstrate that IL-10–secreting RPE capsules markedly improve lung function, suppress fibrotic remodeling, and restore pulmonary architecture in a chronic model of lung fibrosis." (PMID 41356371, 2025). "A relationship was also observed between the markers of progression to pulmonary fibrosis (i.e., YKL-40 and KL-6), IL-6, IL-10, and IL-13 cytokines and mortality." (PMID 36975498, 2023). "In our 14-day BLM model of lung fibrosis, RP-832c also significantly decreased the mRNA expression levels of multiple cytokines, including TNF-α, IL-6, IL-10, and IFN-γ in the lung." (PMID 37174654, 2023). "Overall, we can infer that the use of IL-10 can treat SARS-CoV-2–induced ARDS and pulmonary fibrosis through the anti-viral THαβ immunological pathway, which was previously discussed." (PMID 36914565, 2023). "Third, IL-10 is a potent anti-fibrotic agent that competes with pro-fibrotic cytokines, such as TGF-β, to inhibit pulmonary fibrosis." (PMID 36914565, 2023). "AE improved HFD-induced pulmonary fibrosis by suppressing IL-17, TGF-β, NE, and MMP-9 expression and activating IL-10 and sirt-1 expression." (PMID 35115954, 2021). "For example, the favorable group for pulmonary fibrosis includes IL-1β, IL-4, IL-6, IL11, IL-13, IL-17A, IL-15, and IL-33; in contrast, the other group with anti-fibrotic function has IL-7, IL-10, IL-12, and IL-27." (PMID 35082682, 2021). "Increased levels of IL1ꞵ, IL2, IL6, IL8, IL10, and IL12 have been reported in the bronchoalveolar lavage fluid and/or serum of patients with pulmonary fibrosis compared to healthy subjects." (PMID 34960806, 2021). "A significantly increased lung expression of IL-10 and TGF-β mRNA in lung homogenates from silica-treated mice was observed through the whole process of silica-induced lung fibrosis." (PMID 21072213, 2010). "Lastly, several cytokines involved in TH2 cell recruitment and fibrosis (IL-6, eotaxin, PDGF-ββ, IL-10, IL-1β) were released from macrophages in vitro and correlated with in vivo BAL response, which aligns with KE4 (TH2 cell activation) in the lung fibrosis AOP." (PMID 38509617, 2024). "Similarly, in an established model of lung fibrosis, RP-832c significantly decreased lung fibrosis and significantly decreased inflammatory cytokines TNF-α, IL-6, IL-10, IFN-γ, CXCL1/2, and fibrosis markers TGF-β1 and MMP-13." (PMID 37174654, 2023). "In this study, we found that ZC3H4 could regulate the autophagy pathway to inhibit IL-10 release in monocytes, indicating the complicated and key role of ZC3H4 in pulmonary fibrosis." (PMID 35962397, 2022). "In brief, actions of some of the assessed interleukins in the context of pulmonary fibrosis can be summarized as follows: IL1ꞵ (pro-fibrotic), IL4 (pro and anti-fibrotic), IL6 (pro and anti-fibrotic), IL8 (pro-fibrotic), IL10 (anti-fibrotic), IL12 (anti-fibrotic), and IL13 (pro-fibrotic)." (PMID 34960806, 2021). "The secretion of these factors is thought to lead to the recruitment of innate immune cells to remove these dying cells to regulate inflammation and wound healing, but the release of excessive amounts of IL-10 and TGF-β might contribute to pulmonary fibrosis." (PMID 34859008, 2021). "Mice lacking MMP8 are protected from bleomycin-induced pulmonary fibrosis and their fibroblasts show higher IL-10 levels and lower collagen synthesis, compared to those of wild type mice." (PMID 34072833, 2021). "In the present study, the level of IL-10 in the serum and the lung was elevated after ERC treatment, suggesting that ERCs might protect the mice from pulmonary fibrosis by upregulating IL-10 both locally and systematically." (PMID 30147727, 2018).
pulmonary fibrosis (continued). "To investigate whether ERCs play an anti-inflammatory role in the development and progression of pulmonary fibrosis, we have measured the content of IL-1β, TNF-α, and IL-10 in the serum and the lung tissue." (PMID 30147727, 2018). "In this context, it has been shown that silica-induced lung fibrosis is accompanied in mice by a progressive immunosuppressive process and results from the action of the immunosuppressive cytokines TGF-β and IL-10 produced to limit the development of chronic inflammatory and innate immune responses." (PMID 25050810, 2014). "We additionally show that pulmonary fibrosis in MyD88-KO mice was associated with the accumulation of pro-fibrotic regulatory T lymphocytes (T regs) and pro-fibrotic cytokine expression (TGF-β, IL-10 and PDGF-B), not with T helper (Th) 17 cell influx." (PMID 25050810, 2014). "The Flow Cytometry and realtime PCR study show that Treg cells exert the modulation function both directly by expressing CTLA-4 at the inflammatory stage, and indirectly by secreting increasing amount of IL-10 and TGF-β during the fibrotic stage in silica-induced lung fibrosis." (PMID 21072213, 2010). "Paradoxically, there is a growing body of evidence from animal experiments suggesting that anti-inflammatory cytokines such as IL-10 and TGF-β (which also acts as a potent fibrogenic agent) may also exert a detrimental activity during the establishment of lung fibrosis." (PMID 36768179, 2023). "Transduction of MSC with IL-10 or HGF prevented lung fibrosis after MSC application as both paracrine factors are able to control the unwanted release of TGF-β1 by MSC, which accounted for the tremendous increase in lung fibrosis after naïve MSC transplantation." (PMID 32138309, 2020). "Downregulated expression of TNF-α, IL-1β, IL-6 and IL-10 proteins indicated that AD-MSCs can also protect the lungs from injury and fibrosis through an anti-inflammatory process, which was consistent with ample experimental evidence in MSC-treated pulmonary fibrosis." (PMID 29673394, 2018). "An endotoxin-induced lung fibrosis model in mice showed an MSC-mediated reduction in pulmonary fibrosis via paracrine downregulation of pro-inflammatory responses by reducing TNF-α and macrophage inflammatory protein (MIP)-2 while increasing the anti-inflammatory interleukin (IL)-10." (PMID 26265166, 2015). "We hypothesize that the lack of differences between patients with and without pulmonary fibrosis may be an effect of the influence of other factors like cytokines (tumor necrosis factor, IL-10), immunosuppressive therapy or the predominance of non-active SLE patients in the study." (PMID 24492930, 2014). "It should also be noted that the induced by P. agglomerans significant increase of concentration of antifibrotic cytokines, such as IL10, IL12 and IFNγ does not match the pulmonary fibrosis observed in the histological analysis." (PMID 33999928, 2021). "These human observation are in accordance with several animal data indicating that steroid and numerous anti-inflammatory strategies reduce particle-induced lung inflammation but not IL-10-TGF-β1 expression and lung fibrosis in sensitive animals." (PMID 34489937, 2021). "In IL-10 knockout mice, the protective effects of CRP and SAP on inflammation, nephritis, EAE, and lung fibrosis is reduced or absent, suggesting that these systemic pentraxins can act to quench ongoing inflammatory responses." (PMID 28619036, 2017).